ARLN (allregulin)
Description:
Inhibits the activity of the calcium ATPases ATP2A2/SERCA2 and ATP2A3/SERCA3 by decreasing their apparent affinity for Ca(2+).
Synonyms: ALN; C4orf3; HCVFTP1
Tractability: Antibody: UniProt predicts a signal peptide or a membrane-spanning region.
Gene: Protein-coding gene on chromosome 4 (119,296,419 to 119,304,445, reverse strand). Ensembl gene ENSG00000164096.
Subcellular location: Endoplasmic reticulum membrane
Subcellular location (Human Protein Atlas): Endoplasmic reticulum
Gene Ontology:
Cellular component: endoplasmic reticulum membrane
Genetic constraint (gnomAD): Loss-of-function variants: 5 observed, 6.89 expected, observed/expected ratio (o/e) 0.73, 90% interval 0.38 to 1.5. That is too few expected variants to judge how well the gene tolerates losing a copy. Missense variants: 86 observed, 88.94 expected, observed/expected ratio (o/e) 0.97, 90% interval 0.81 to 1.16. Synonymous variants: 34 observed, 34.83 expected, observed/expected ratio (o/e) 0.98, 90% interval 0.74 to 1.3.
Homologues: Orthologues: chimpanzee C4H4orf3 (98% identical), mouse Arln (68% identical), pig ARLN (65% identical), dog C32H4orf3 (64% identical), rat C2h4orf3 (64% identical), guinea pig ARLN (53% identical).
Diseases named in the same sentence as ARLN in open-access papers:
ARLN is named in the same sentence as 14 diseases in open-access papers, as found by Europe PMC text mining. Sharing a sentence is not in itself a finding about the gene and the disease.
ARLN shares sentences with these, for which no sentence is quoted: cancer (2 papers); tumor (2); coronary artery disease (1); endometriosis (1); heart disease (1); Hyperglycemia (1); Insulin resistance (1); lung adenocarcinoma (1); Obesity (1); osteosarcoma (1); pancreatic cancer (1); small cell lung carcinoma (1); Stroke (1); type 2 diabetes (1).